CRP (C-reactive protein)
Diseases named in the same sentence as CRP in open-access papers (continued):
Sharing a sentence is not in itself a finding about the gene and the disease.
cancer (continued). "The underlying mechanism of the relationship between CRP and cancers are that tumor growth can cause tissue inflammation, which make cancerous cells secrete interleukin 6 (IL-6) and stimulate CRP production in liver 35-37." (PMID 33613752, 2021). "Regarding laboratory values, lower levels of hemoglobin, higher levels of D-dimers, elevated ESR, and elevated levels of CRP have been linked to cancer patients." (PMID 33945004, 2021). "In patients with bladder and kidney cancers, CRP levels have been associated with disease progression, stage, and cancer-specific survival." (PMID 34512646, 2021). "The present study demonstrates a significant reduction in length of hospital stay, intraoperative blood loss, and inflammatory stress response measured by CRP in patients undergoing colorectal resection for cancer with RCS compared to the LCS." (PMID 34022914, 2021). "Several factors are as expected more common in unresectable patients, for example, involuntary weight loss, older age, higher C-reactive protein (CRP), and cancer antigen (CA) 19-9." (PMID 32299289, 2021). "The present study identifies multiple BM, infratentorial location of the metastatic lesion, elevated initial CRP-levels and advanced frailty scoring as risk factors for worsened OS in elderly cancer patients that undergo surgery for BM." (PMID 34381733, 2021). "PTX3, a modulator of inflammatory processes, is a member of the highly conserved pentraxin superfamily, which includes CRP, and it is associated with disease severity and mortality in patients with cancer." (PMID 33776564, 2021). "Investigations into CRP as a measure of risk for cancer development are part of what makes this marker intriguing." (PMID 34926085, 2021). "Systemic inflammation measured by the acute-phase protein CRP associates with poor outcome across cancer types." (PMID 34531864, 2021). "Researchers generally believe that PD causes cancer mainly by affecting systemic immune response which leads to the increase of serum inflammatory markers, and moreover, the level of C-reactive protein particularly increases with the progress of PD." (PMID 33247563, 2021). "C-reactive protein (CRP) and fibrinogen are acute-phase proteins and markers of inflammation associated with cancer and cardiovascular disease." (PMID 34210304, 2021). "Studies indicate an association between CRP and cancer mortality, particularly for colorectal cancer." (PMID 34210304, 2021). "Similar to the entire cohort, reduced or elevated platelet count (p = 0.011 and p < 0.001), elevated levels of D-dimers (p = 0.014 and p = 0.027) and CRP (p < 0.001 and p = 0.011) were associated with cancer in women and in men." (PMID 33945004, 2021). "The common conditions associated with elevations of CRP levels are bacterial infection, inflammatory diseases, cancer, tissue necrosis and trauma 26-28." (PMID 33613752, 2021). "The most significant association of inflammatory parameters with cancer risk were detected for CRP (39.8%), fibrinogen (24%), IL6 (25%) and TNFα (24%)." (PMID 34685542, 2021). "For example, C-reactive protein (CRP), a diagnostic marker of cancer cachexia, is synthesized in the liver in response to systemic IL-6." (PMID 33801569, 2021). "An increase in CRP concentration has been shown to be associated with poorer survival in cancer patients, not only in the palliative situation but also with primary operable cancer." (PMID 34884980, 2021). "Peripheral blood CRP level was also associated with improved OS in the c4G12 treatment group, consistent with a previous report of cancer patients who were treated with anti-PD-1/PD-L1 therapy." (PMID 33580183, 2021). "Accordingly, they showed that the GPS, which considers a combination of albumin and CRP levels, was an independent risk factor for poor prognosis and cancer recurrence." (PMID 33435255, 2021).
cancer (continued). "The expression of CRP is influenced by different cytokines and cytotoxic factors that are linked to cancer cell proliferation, growth, and migration." (PMID 34070592, 2021). "Several studies have reported the association of GlycA and GlycB with key markers of cancer stratification, such as CRP." (PMID 34344464, 2021). "While the association between CRP and systemic inflammation in cancer patients is generally accepted, little is known about the significance of serum CRP levels and the local immune status of the tumor." (PMID 35070979, 2021). "For instance, 15% of patients with cardiovascular disease, after a median follow-up of 8.3 years, developed different types of cancer whose incidence was associated with high C-reactive protein (CRP) levels." (PMID 34447383, 2021). "The overall estimates have shown a 11% increase in the risk of all cancers for increased natural logarithm levels of CRP." (PMID 33671768, 2021). "Inflammatory markers like elevated C-reactive protein (CRP) have shown to be associated with a poor prognosis in cancers." (PMID 34722011, 2021). "Multivariate Cox regression analyses revealed that age ≥ 60 years, men, neutrophil counts, lymphocyte counts, platelet counts, hs-CRP and cancer were independently associated with IMV therapy, ICU admission and ARDS." (PMID 33761466, 2021). "CRP is a systemic marker of chronic inflammation and has been reported as a risk factor for cancer development." (PMID 34915912, 2021). "In the literature, CRP is one of several inflammatory biomarkers associated with frailty in older patients with cancer." (PMID 35008333, 2021). "Two meta-analyses, have found that elevated pretreatment CRP is associated with worse overall survival, cancer-specific survival, progression-free survival, and biochemical recurrence-free survival." (PMID 34512646, 2021). "In multivariable Cox regression, risk for death was associated with cancer (HR 1.7), low hemoglobin (HR 2.6), mRS on admission ≥ 4 (HR 1.9), pathologic platelet count (HR 1.6), female sex (HR 1.7), and elevated CRP (HR 1.4)." (PMID 33945004, 2021). "Elevated NLR and/or elevated CRP have been associated with poor survival after chemotherapy in various cancers." (PMID 32824226, 2020). "CRP, a reliable marker of systemic inflammation, reflects cell-mediated immunity associated with poor outcomes in several cancers." (PMID 33227100, 2020). "C-reactive protein (CRP) is a sensitive marker of an infectious or inflammatory disease state and is also an important hallmark of carcinogenesis and cancer progression." (PMID 33227100, 2020). "Nevertheless, these were difficult to reconcile with the established positive association between cancer risk and circulating CRP levels." (PMID 32477370, 2020). "Confusingly, the identified variants can be associated with increased cancer risk but with decreased levels of circulating CRP." (PMID 32477370, 2020). "CRP and V ̇o2peak were independently associated with major complications after potentially curative oesophagectomy for cancer." (PMID 32749071, 2020). "In particular, IL-6 is an important mediator of CRP production and is associated with cancer cell growth; CRP correlates to IL-6 concentrations in tumors." (PMID 32309219, 2020). "LPC levels are decreased in cancer, associated with weight loss and increased inflammation, where they inversely correlate with CRP levels in plasma." (PMID 32599910, 2020). "We showed that individuals with higher CRP levels at baseline had a greater risk of cancer mortality, in line with several other studies." (PMID 31936330, 2020). "In OSCC patients, mGPS is a potential independent prognostic factor of cancer-specific survival and OS (Farhan-Alanie, McMahon & McMillan, 2015), and preoperative circulating CRP levels are associated with pathological aggression and survival outcomes." (PMID 32587804, 2020).
cancer (continued). "In this current report of over 10,000 men and women, we found that higher CRP was associated with increased cancer mortality among males." (PMID 33243216, 2020). "Higher levels of CRP and ferritin were also associated with more severe COVID-19 disease in infected cancer patients." (PMID 32903324, 2020). "Various previous studies demonstrate an association between the pre-treatment plasma CRP level and prognostic outcome in different cancer entities, including CRC." (PMID 33023215, 2020). "An association between elevated CRP levels and poor prognosis has been detected in different cancer entities including HNSCC." (PMID 32182693, 2020). "Many recent studies have reported an association between high CRP levels and poor prognosis as well as progressive disease in patients with a variety of cancers, including lung, kidney, colorectal, breast, and ovarian cancers." (PMID 32974174, 2020). "Lower SEP and certain socio-behavioral patterns have been shown to be inversely correlated with CRP and fibrinogen, and higher systemic inflammation increases the risk of cancer diagnosis." (PMID 33243216, 2020). "IL33Rα showed an association of borderline significance with cancer-related death, whereas highly significant associations were observed for the tumor characteristics and CRP levels." (PMID 32707675, 2020). "A recent meta‐analysis showed a reliable association between inflammatory markers (including CRP, IL‐1, and IL‐6) and self‐reported depressive symptoms, although studies on cancer patients remained extremely limited (Howren, Lamkin, & Suls, 2009)." (PMID 32790154, 2020). "CRP/Alb ratio was considered to be associated with the inflammatory response induced by cancer progression processes, such as tumor growth, invasion, necrosis, hypoxia, or local tissue damage." (PMID 32856868, 2020). "In a HF Japanese registry, the risk of developing cancer was present in those who had a baseline C-reactive protein (CRP) value > 2.0 mg/dL (HR 1.87) and remained high after one year." (PMID 32532011, 2020). "The possible mechanism is that the systemic inflammation caused by malignant tumors can releases a large number of pro-inflammatory mediators, such as CRP, fibrinogen, VEGF, and TGF-α." (PMID 32426277, 2020). "It was reported that there is a positive association between elevated circulating CRP levels and the risk of cancer." (PMID 33036573, 2020). "Chronic systemic low-grade inflammation is related to a higher risk of incident cancer, as suggested by the results of previous prospective cohort studies which found an increased risk of incident cancer related to higher C-reactive protein levels." (PMID 32708201, 2020). "In Kaplan–Meier analyses, only IL6 (p = 0.036) showed a significant association with cancer-specific survival, whereas CRP (p = 0.075) and CNTF (p = 0.084) demonstrated borderline values." (PMID 33066437, 2020). "A comprehensive review of the literature on the diagnostic significance and therapeutic value of CRP blood levels in cancer proved to be problematic." (PMID 33324413, 2020). "Another complicating factor in interpreting the diagnostic and therapeutic value of CRP in cancer disease is the current focus on the value and significance of “high sensitivity CRP” levels (i.e. hsCRP)." (PMID 33324413, 2020). "It has been emphasized that raised levels of CRP inversely correlate with survival in cancer patients and increase the risk of developing cancer in the overall population." (PMID 33096884, 2020). "An increase in C reactive protein (CRP) implicated an increased risk for cancer of 2.4% (OR: 1.024, 95%CI: 1.001–1.047; p = 0.041)." (PMID 33291857, 2020). "A causal involvement suggests that genetically elevated levels of circulating CRP would affect cancer risk." (PMID 32477370, 2020). "There have been several large-scale studies investigating the associations between genetic CRP variants and cancer risk in European, American and Chinese populations." (PMID 32477370, 2020).
cancer (continued). "Cancer cell invasion and tumor necrosis can positively upregulate systemic inflammatory response, and the inflammatory marker CRP has been previously determined to exhibit an association with survival outcomes in OSCC patients." (PMID 32587804, 2020). "In the full Cox multivariate model, clinically raised CRP was associated with cancer mortality in the NHANES III (> 0.99 mg/dL: 95%CI: 1.04–2.13)." (PMID 33243216, 2020). "Some studies revealed that neutrophil to lymphocyte ratio (NLR) and C-reactive protein (CRP) were associated with prognosis in several types of cancers, including EC 6-9." (PMID 32047540, 2020). "In the full Cox multivariate model, clinically raised CRP was associated with cancer mortality in NHANES 1988–1994 (> 0.99 mg/dL: 95%CI: 1.04–2.13)." (PMID 33243216, 2020). "In line with previous findings, our cohort demonstrated that an increase in CRP is associated with an increased risk for cancer of 2.4% in PMR/GCA patients." (PMID 33291857, 2020). "In an additional exploratory logistic regression analysis, an increase in CRP implicated, on average, an increased risk for cancer of 2.4% (OR: 1.024, 95% CI: 1.001–1.047; p = 0.041), when the cancer was either a solid cancer or MGUS (n = 8)." (PMID 33291857, 2020). "In the USA, CRP is the second and third most important cause of cancer‐related deaths among male and female patients, respectively." (PMID 33201589, 2020). "We also genotyped the most frequently examined CRP variant, rs1205, and another CRP promoter variant, rs2794521, in a subgroup of 489 healthy controls and 1116 cancer patients using TaqMan assays." (PMID 32477370, 2020). "The pathophysiological role of CRP as an acute-phase protein has been extensively investigated, but the causal relationship between raised CRP and poor survival in cancer patients seems unclear." (PMID 32423000, 2020). "The objectives of this study were to evaluate the diagnostic significance of ECPKA‐Ab in canine malignancy and to determine if combined measurement of CRP and ECPKA‐Ab levels in serum improves diagnostic accuracy for detection of cancer in dogs." (PMID 30411459, 2019). "Postoperative increases in inflammatory markers, including cytokines and CRP, are associated with tissue damage, postoperative morbidity, and cancer recurrence." (PMID 30918320, 2019). "The presence of proinflammatory cytokines and TNFs in the tumor microenvironment is one of the causes of elevated serum CRP in patients with malignant tumors." (PMID 31662753, 2019). "Associations between higher levels of CRP, the most validated inflammatory marker, and poor appetite have been reported in hemodialysis and cancer patients." (PMID 31443557, 2019). "Inflammatory markers such as CRP, albumin, neutrophil, and lymphocyte count have been associated with mortality in numerous cancer types." (PMID 31096693, 2019). "This study examined the diagnostic utility of inflammatory markers (C-reactive protein, erythrocyte sedimentation rate and plasma viscosity) for cancer diagnosis in primary care." (PMID 31015558, 2019). "A host of studies provided compelling evidence that high CRP levels were associated with a poor prognosis in cancer patients, including LC." (PMID 31142628, 2019). "Several systemic inflammation-based prognostic biomarkers have been identified, such as NLR, PLR, lymphocyte-to-monocyte ratio and C-reactive protein, as potential cancer risk or prognostic factors." (PMID 31192131, 2019). "A positive association between CRP levels and mortality in disease-free individuals, as well as in cancer patients is reported in the literature." (PMID 31652816, 2019). "For example, elevated serum CRP is prospectively associated with a number of cancer types, including colon, breast and lung." (PMID 31622379, 2019). "Higher levels of CRP were associated with suppressed appetite and food intake in dialysis patients and in cancer patients." (PMID 31443557, 2019).
cancer (continued). "CRP has been reported to be associated with reduced serum albumin, resulting in progressive weight loss, poor performance, and higher mortality in cancer patients with systemic inflammation." (PMID 30941358, 2019). "ECPKA‐Ab and CRP levels were detected by an enzyme‐linked immunosorbent assay in serum samples from dogs with malignant tumours (n = 167), benign tumours (n = 42), or non‐tumour disease (n = 155) and from healthy control dogs (n = 123)." (PMID 30411459, 2019). "There is a substantial body of literature describing the association between prognosis and C-reactive protein in patients with cancer." (PMID 30097610, 2018). "Cancer patients who are deficient in AA tend to have lower plasma concentrations after infusion; in fact, high tumour burdens measured by CRP and other markers tend to decrease AA plasma levels." (PMID 30217071, 2018). "The relationship between high concentrations of CRP and the risk of different cancers was demonstrated by several studies." (PMID 30065196, 2018). "First, a causality model has been proposed wherein chronic inflammation causes the elevation of CRP levels, which initiates the formation of malignant tumors." (PMID 29668751, 2018). "A reduction of CRP and IL-6 by PA is also beneficial since there is an increased vascular risk with high levels of these biomarkers and even some cancers." (PMID 29401699, 2018). "In our study, male gender, ASA ≥3, weight loss, open wound, relapse of cancer metastasis and laboratory data including low serum albumin, low Na level and elevated C‐reactive protein (CRP) levels were identified as predictors." (PMID 29863168, 2018). "The association between inflammation and cancer is well documented, and serum C-reactive protein (CRP) concentrations have been correlated with the aggressiveness of PC." (PMID 29662668, 2018). "Numerous epidemiological studies have showed that elevated CRP has been correlated with persistent fatigue, increased weight loss, low performance status and poor survival of cancer patients." (PMID 29568406, 2018). "Research showed that several inflammation markers are associated with cancer, such as inflammation-based prognostic score based on C-reactive protein(CRP )and albumin levels." (PMID 29515785, 2018). "High CRP is most likely to be associated with tumor necrosis, local tissue damage, and inflammation response in cancer patients." (PMID 29193777, 2018). "As a typical representative of inflammatory reactions, C-reactive protein (CRP) has been reported to be significantly associated with the prognosis of several cancers." (PMID 29211406, 2018). "The mGPS combines albumin and CRP into a prognostic risk stratification score for predicting the clinical outcome in cancer patients." (PMID 29467943, 2018). "An elevated CRP level was reported to be associated with a poorer prognosis in various types of human cancers." (PMID 29890986, 2018). "Pro-inflammatory cytokine activity increases during cancer progression, and systemic inflammation is the hallmark of cancer cachexia indicated by production of acute-phase response (APR) proteins such as C-reactive protein and fibrinogen." (PMID 28177923, 2017). "The underlying mechanism is that CRP can accelerate angiogenesis based on increased circulating levels of vascular growth factors and circulating interleukin in cancer patients." (PMID 28431566, 2017). "Elevated plasma levels of CRP are not only associated with a wide variety of inflammatory diseases but also some forms of cancer." (PMID 29202702, 2017). "IL-1β levels strongly associated with subjective (weight loss, loss of appetite) and objective (albumin and CRP levels) measurements of cancer cachexia." (PMID 28177923, 2017). "Age, PSA, PSA density (PSAD), serum monocyte fraction of WBC, monocyte-to-lymphocyte ratio (MLR), and CRP were significantly associated with high Gleason score cancer (p<0.01)." (PMID 27823973, 2017).